SOX9 (SRY-box transcription factor 9)
Diseases named in the same sentence as SOX9 in open-access papers (continued):
Sharing a sentence is not in itself a finding about the gene and the disease.
cyst (3 papers, 2020 to 2022). A sac-like closed membranous structure that may be empty or contain fluid or amorphous material. "The tubular structure in the triple co-culture was highly differentiated from the cyst, as shown by significant changes in Sox9 and Cftr expression." (PMID 32206088, 2020). "Thus, defective branching from SOX9+ cells failed to produce the conducting airways and led to cyst formation in Tfamf/f; ShhCre/+ and Cox10f/f; ShhCre/+ lungs." (PMID 36433959, 2022).
diffuse large B-cell lymphoma (3 papers, 2023 to 2025). "However, SOX9 is overexpressed in certain types of B-cell lymphomas, like Diffused Large B-cell Lymphoma (DLBCL), where it acts as an oncogene by promoting cell proliferation, inhibiting apoptosis, and contributing to the cancer’s progression." (PMID 41293317, 2025).
Endometrial adenocarcinomas (3 papers, 2021 to 2024). "In the same study, the authors correlated the clinical stages of endometrial adenocarcinomas with the three clusters of the SOX9+ population." (PMID 37353907, 2023). "Endometrial adenocarcinomas have two main signatures, SOX9+LGR5+ and SOX9+LGR5−, indicating that these distinct transcriptomic signatures reflect differences in pathogenesis and disease progression." (PMID 34857954, 2021). "Endometrial adenocarcinomas displayed two main signatures that were characteristic of the proliferative phase endometrium, SOX9+LGR5+ and SOX9+LGR5−, indicating differences in pathogenesis and disease progression." (PMID 39229264, 2024). "The more advanced stages of endometrial adenocarcinomas (stages III and IV) were found to have a greater SOX9+LGR5+ signal." (PMID 37353907, 2023). "The more advanced stages of endometrial adenocarcinomas (stages III and IV) have a greater SOX9+LGR5+ signal (Wilcoxon test, stages I + II against stages III + IV, P value 7.54 × 10−6)." (PMID 34857954, 2021).
endometrioid adenocarcinoma (3 papers, 2021 to 2024). An adenocarcinoma characterized by the presence of malignant glandular epithelial cells resembling endometrial cells. "SOX9+LGR5+ is the dominant signature in serous endometrial and some endometrioid adenocarcinomas and is positively associated with the ‘Copy-Number high’ molecular subtype from TCGA, as well as the clinically more aggressive stage III and IV adenocarcinomas." (PMID 34857954, 2021). "SOX9+LGR5+ was the dominant signature in serous endometrial (63%) and some endometrioid adenocarcinomas (24%) and was positively associated with the ‘Copy-Number high’ molecular subtype from TCGA, as well as the clinically more aggressive stage III and IV adenocarcinomas." (PMID 39229264, 2024). "Indeed, all the copy-number-high tumors considered in our analysis (31 serous and 7 serous-like endometrioid adenocarcinomas) were classified as SOX9+LGR5+." (PMID 34857954, 2021). "The first, characterized by SOX9+LGR5+, occurs in 63% of serous and 24% of endometrioid adenocarcinomas." (PMID 34857954, 2021). "The second, SOX9+LGR5−, is found in 33% of endometrioid adenocarcinomas but is absent from serous adenocarcinomas." (PMID 34857954, 2021).
gastric tumor (3 papers, 2019 to 2022). "REG4 expression upregulates SRY-box transcription factor 9 (SOX9) and promotes invasiveness and migration in gastric tumor cells." (PMID 33489872, 2020). "In conclusion, this is the first study to report that the absence of SOX9 protein expression in gastric tumours predicts a significant risk of relapse." (PMID 31275454, 2019).
Glucose intolerance (3 papers, 2011 to 2024). Glucose intolerance (GI) can be defined as dysglycemia that comprises both prediabetes and diabetes. "Additionally, by characterizing the adult phenotype of Sox9-haploinsufficient mice, we show that reduction of Sox9 gene dosage causes glucose intolerance." (PMID 21829703, 2011). "Phenotypes have been observed in heterozygote animals previously in the context of the pancreas; for example, heterozygote Sox9 mice showed glucose intolerance and endocrine formation defects, suggesting that they can provide insights into important biology." (PMID 39159974, 2024). "We adopted a Cre-lox knockout approach to delete Sox9 in mouse cells at the time of beta cell specification, and found that with time, transgenic animals developed glucose intolerance, similar to what is seen in patients with T2D." (PMID 38238288, 2024). "Our results show that Sox9-depleted rodent beta cells have defective insulin secretion, and aging animals develop glucose intolerance, mimicking the progressive degeneration observed in T2D." (PMID 38238288, 2024). "Consistent with developing glucose intolerance, by six weeks of age, blood glucose levels were significantly elevated in Sox9+/Δpan mice compared with control littermates following an acute glucose challenge." (PMID 21829703, 2011). "We further show that reduced beta-cell mass in Sox9-haploinsufficient mice leads to glucose intolerance during adulthood." (PMID 21829703, 2011). "Glucose intolerance persisted in Sox9+/Δpan mice at 12 weeks of age and later time points." (PMID 21829703, 2011). "Thus, pancreatic Sox9-haploinsufficiency results in glucose intolerance." (PMID 21829703, 2011).
heart failure (3 papers, 2018 to 2025). Inability of the heart to pump blood at an adequate rate to meet tissue metabolic requirements. "CHIA-FENG LIU and colleagues analyzed RNA levels in cardiac tissue samples from heart failure patients using whole-transcriptome sequencing, finding significant upregulation of SOX9 RNA in patients with dilated cardiomyopathy and hypertrophic cardiomyopathy." (PMID 39974732, 2025). "Our bioinformatics revealed downregulation of miR–129-5p and upregulation of its targets small leucine–rich proteoglycan Asporin (ASPN) and transcription factor SOX9 as common in mouse and human heart failure (HF)." (PMID 37154157, 2023). "Loss of Sox9 is embryonic lethal; it is believed that null embryos die as a result of heart failure, though it is not known whether this is due to valve malformations or loss of Sox9 in other cardiac cell types." (PMID 30224706, 2018).
hydronephrosis (3 papers, 2014 to 2024). Collection of urine in the renal pelvis that results in dilatation of the renal pelvis and calyces. "Interestingly, in vivo inactivation of Sox9 or Myocd in mice also causes hydronephrosis/proximal hydroureter or megabladder due to disruption of SM cell differentiation during urogenital system development." (PMID 39420202, 2024). "In the kidney, Sox9 deficiency leads to hydronephrosis and renal hypoplasia." (PMID 34215331, 2021). "Deletion of Sox9 in ureteral mesenchyme results in hydroureter and hydronephrosis, mimicking defects in Smad4CKO embryos." (PMID 25127126, 2014).
hypospadias (3 papers, 2021 to 2025). Hypospadias is the displacement of the urethral meatus on the ventrum of the penis. "Of note, MAPK signaling can alter the proper action of downstream SRY-Box transcription actor 9 (SOX9) and the mutation of SOX9 can progress the development of hypospadias." (PMID 39624466, 2025). "Reports suggest that mutations in SOX9 are responsible for hypospadias." (PMID 40626133, 2024). "All the effects of SOX9 on testis development, sex differentiation and hormone secretion suggest a linkage between SOX9 and hypospadias development." (PMID 39624466, 2025). "We therefore postulate that insufficient expression of SOX9 results in the development of hypospadias by lessening the Wnt signaling pathway, which consequently leads to anomalous EMT." (PMID 40626133, 2024). "Experiments using siRNA to inhibit SOX9 expression in foreskin fibroblasts yielded similar results to the hypospadias group." (PMID 40626133, 2024). "Discovering fresh molecular mechanisms of SOX9 can enhance the comprehension of SOX9's pathogenesis in hypospadias, which holds immense significance." (PMID 40626133, 2024). "We confirmed the presence and down‐regulation of SOX9 in hypospadias samples through RT‐PCR and Western Blot analysis." (PMID 40626133, 2024). "Furthermore, our immunofluorescence results highlighted significantly lower expression of SOX9 in the hypospadias foreskin group compared to the normal foreskin group." (PMID 40626133, 2024). "However, the roles of SOX9‐dependent genes and pathways in normal urethral development and the mechanism of hypospadias are unclear." (PMID 40626133, 2024). "The findings suggest that down‐regulation of SOX9 expression may contribute to the development of hypospadias by down‐regulating the WNT pathway and inhibiting EMT." (PMID 40626133, 2024). "Therefore, this study aims to investigate the mechanism of SOX9 in hypospadias to fill this gap." (PMID 40626133, 2024). "We utilized RT‐PCR and Western blot techniques to investigate the Wnt signaling pathway and observed a significant reduction in both mRNA and protein levels of SOX9, Wnt3a, LEF1, GSK3β, NF‐κB, TCF1, and cyclin D1 in the samples of hypospadias." (PMID 40626133, 2024). "It was found that mRNA and protein levels of SOX9, WNT signaling pathway, and EMT mesenchymal markers were significantly reduced in the hypospadias group compared to the normal foreskin group." (PMID 40626133, 2024). "To investigate the roles of SOX9, WNT/β‐catenin signaling and EMT in hypospadias progression, we analyzed foreskin tissues obtained from children with hypospadias." (PMID 40626133, 2024). "Compared with normal foreskin, we observed reduced expression of SOX9, Wnt/β‐catenin pathway signaling and mesenchymal markers Vimentin and α‐SMA in hypospadias tissue." (PMID 40626133, 2024). "The inhibition of SOX9 in mesenchymal cell may mediates the aberrant expression of the Wnt/β‐catenin signaling pathway EMT process, leading to the development of urethral hypospadias." (PMID 40626133, 2024).
intestinal tumor (3 papers, 2016 to 2024). "ELP3 is also found to be required for Sox9 translation and maintenance of a subset of Lgr5+/Dclk1+/Sox9+ cells which is crucial for Wnt-driven intestinal tumor initiation and radiation-induced regeneration." (PMID 37771073, 2024).
liver inflammation (3 papers, 2023 to 2025). "Activation of macrophage NR4A1 or SOX9 in Caspase 6-deficient livers aggravated liver inflammation." (PMID 36977670, 2023).
metastasis (3 papers, 2018 to 2025). The spread or migration of cancer cells from one part of the body (where they first appeared) to another. "Our clinical pathological analysis showed a strong correlation between SOX9 protein expression and ALDH1 protein expression only in metastatic HGOC samples, indicating an association among SOX9 expression, platinum drug resistance, and lymph node metastasis." (PMID 35159173, 2022).
Myocardial fibrosis (3 papers, 2021 to 2023). "Together, we demonstrate miR–129-5p/ASPN and miR–129-5p/SOX9 as potentially novel dysregulated axes in CF-to-MF and CF-to-OF transition in myocardial fibrosis and calcification and the therapeutic relevance of miR–129-5p." (PMID 37154157, 2023). "The research confirmed that BEL blocks SOX9 to regulate TGF-β signalling to ameliorate myocardial fibrosis." (PMID 35586685, 2022). "Recently, SOX9 was proposed as a potential therapeutic target for myocardial fibrosis because of ischemia-reperfusion injury." (PMID 35586685, 2022). "BEL appears to alleviate myocardial fibrosis by inhibiting SOX9 to suppress the elevations in α-SMA, Collagen I, and III." (PMID 35586685, 2022). "Together, these data show dysregulated expression of miR–129-5p and its targets ASPN and SOX9 in mouse LV and human CF in the context of nonischemic HF associated with myocardial fibrosis and calcification." (PMID 37154157, 2023). "Importantly, miR–129-5p mimic not only attenuated progression of myocardial fibrosis, calcification marker expression, and SOX9 and ASPN expression in CF but also restored diastolic and systolic function." (PMID 37154157, 2023). "SOX9 is regarded as a new target regulating myocardial fibrosis." (PMID 35586685, 2022). "SRY-related high mobility group-box gene 9 (SOX9) is a new target regulating myocardial fibrosis." (PMID 35586685, 2022). "In conclusion, BEL may provide a new therapeutic strategy by targeting SOX9 against myocardial fibrosis." (PMID 35586685, 2022). "Increasing attention has been paid to SOX9 in myocardial fibrosis." (PMID 35586685, 2022). "In vivo study verified that BEL ameliorated myocardial fibrosis by inhibiting SOX9." (PMID 35586685, 2022). "Therefore, BEL inhibited SOX9 to block TGF-β1 signalling activation to ameliorate myocardial fibrosis." (PMID 35586685, 2022). "To assess whether the attenuation of myocardial fibrosis and calcification progression by miR–129-5p may be explained by differences in expression of SOX9 and ASPN in CF, we employed lineage tracing of CF of the transcription factor 21 (Tcf21) lineage in mice (Tcf21MCM/+;R26EGFP mice)." (PMID 37154157, 2023). "Targeting SOX9 in fibroblasts could improve myocardial fibrosis by regulating AKT/GSK-3β/β-catenin." (PMID 35586685, 2022). "We experimentally confirmed decreased miR–129-5p and enhanced SOX9 and ASPN expression in CF in human hearts with myocardial fibrosis and calcification." (PMID 37154157, 2023). "However, it is unclear whether BEL can regulate SOX9 to alleviate myocardial fibrosis." (PMID 35586685, 2022). "Here, we investigate the relationship between TGF-β signalling and SOX9 in cardiac fibroblast and explore the mechanism of BEL against myocardial fibrosis to provide a new strategy for heart failure therapy." (PMID 35586685, 2022). "Since both SOX9 and ASPN were validated to be upregulated in LV upon chronic AngII infusion, we pursued this in vivo model to further investigate the role of miR–129-5p in myocardial fibrosis and calcification in mice." (PMID 37154157, 2023). "However, the relationship between SOX9 and TGF-β1 signalling remains unclear in fibroblasts involved in myocardial fibrosis." (PMID 35586685, 2022).
pituitary tumor (3 papers, 2021 to 2024). A benign or malignant neoplasm affecting the pituitary gland. "Due to our data, the overexpression of the SOX9 gene level was observed in pituitary tumor tissues in comparison to normal tissues which was associated with an elevated level of SOX9 protein in tumor tissues." (PMID 33736633, 2021). "In GH-secreting pituitary tumor tissues as prevalent pituitary tumors, the increased level of SOX9 was observed in tumors with bigger in size and invasive features which is in line with the impressive role of SOX9 in cell proliferation and invasion." (PMID 33736633, 2021). "Accordingly, the invasive GH-producing pituitary tumors expressed a higher level of SOX9 comparing to non-invasive tumors also the higher protein level of SOX9 was observed in invasive tumors." (PMID 33736633, 2021). "Based on our data, 14.28% of invasive GH-producing pituitary tumors showed weak expression of SOX9 protein expression (Score 1+), while 85.71% of invasive tumors revealed a moderate level of SOX9 protein (Score 2+)." (PMID 33736633, 2021). "Also, the relevance of SOX9 with pituitary tumor size was confirmed by the assessment of SOX9 protein level in our patients’ tumor sections, and it was revealed that all of the macroadenoma pituitary tumors expressed SOX9 protein." (PMID 33736633, 2021). "As it was observed from our results, SOX9 over-expressed in GH-secreting tumor tissues and the differences in its expression level were significant between tumor subtypes such as macro adenoma tumors and invasive GH-producing pituitary tumors." (PMID 33736633, 2021). "Another study utilised immunofluorescence in human pituitary tumours to demonstrate expression of stem cell markers, SOX2 and SOX9, in a variety of clinical tumour types." (PMID 38483762, 2024). "Furthermore, it was demonstrated that SOX2 and SOX9 expressing progenitor cells can self-renew and give rise to endocrine cells in vivo, suggesting that they are tissue stem cells, playing a role in the physiological maintenance of the pituitary gland as well as in the induction of pituitary tumors." (PMID 35805171, 2022). "However, 38.46% of non-invasive GH-producing pituitary tumors showed no expression of SOX9 protein while 23.07 and 38.46% of non-invasive tumors showed weak and moderate expression of SOX9 protein (Score 1+, Score 2+, respectively)." (PMID 33736633, 2021). "In addition, 25% of GH-producing pituitary tumors showed no expression of SOX9 while 20 and 55% of tumors revealed a weak and moderate SOX9 protein expression (Score 1+, Score 2+), respectively." (PMID 33736633, 2021). "Regarding invasive pituitary tumors, it was revealed that the SOX9 gene expression was significantly correlated with its protein expression level (P = 0.01), while the correlation between SOX9 gene and protein expression was not significant in non-invasive tumors." (PMID 33736633, 2021).
retinal degeneration (3 papers, 2023 to 2025). Degeneration of the retina. "We found that, after Sox9 ablation, mutant mice undergo a severe process of retinal degeneration characterized by the loss of MG cells and complete depletion of the photoreceptors layer." (PMID 41190718, 2025). "The main reason is probably that these studies focused on the developing retina and are therefore not useful for understanding how the absence of Sox9 in MG and RPE cells in the adult eye leads to the retinal degeneration observed in our Sox9-deficient adult mutants." (PMID 41190718, 2025). "Thus, screening of the SOX9 regulatory region may provide new molecular mechanisms underlying idiopathic cases of retinal degeneration." (PMID 41190718, 2025). "We conditionally deleted Sox9 in the adult mouse retina and observed a phenotype characterized by different degrees of retinal degeneration." (PMID 41190718, 2025). "In summary, through functional analyses in mice, we have demonstrated multiple roles for Sox9 in the adult eye, acting as an essential maintenance factor preventing retinal degeneration on the one hand, and promoting the differentiation of limbal cells in the cornea on the other." (PMID 41190718, 2025). "This is probably because CD patients are mostly heterozygous for SOX9 and show early postnatal lethality, so a retinal degeneration phenotype in adulthood was either overlooked or not addressed." (PMID 41190718, 2025). "However, RPE-specific deletion of Sox9 does not induce retinal degeneration and in fact results in Otx2 upregulation, suggesting that Sox9 is not an upstream regulator of Otx2 in this context." (PMID 41190718, 2025). "However, SOX9 in the inner nuclear layer (INL), where Muller glia expresses SOX9, was strongly and widely detected on day 3, suggesting that Muller glia is activated by oxidative stress and resultant retinal degeneration." (PMID 37185874, 2023). "Since photoreceptors are absent in severely affected Sox9-mutant retinas, we conducted TUNEL assays to study the role of cell death in the process of retinal degeneration." (PMID 41190718, 2025).